TNF (tumor necrosis factor)
Diseases named in the same sentence as TNF in open-access papers (continued):
Sharing a sentence is not in itself a finding about the gene and the disease.
tumor (continued). "Macrophages play an important role in tumor growth and progression as they produce a large quantity of cytokines such as tumor necrosis factor-α (TNF-α), interleukin-10 (IL-10), and interferon-γ (IFN-γ)." (PMID 29361917, 2018). "TNFα released by tumor cells and cells of TME acts through its receptor TNFR1 and further reinforces TNFα expression and the inflammatory and immune-modulatory network including CXCL12, CCL2, IL-6, VEGF, and macrophage inhibitory factor." (PMID 30154786, 2018). "TNF-α plays a very important role in the host defense mechanism and has a direct killing effect on tumor cells." (PMID 30296293, 2018). "Our sequencing results revealed that TNFα plays a crucial role in the development of a pro-invasion tumor phenotype through the up-regulation of genes involved in several cancer pathways, particularly matrix remodeling and inflammation." (PMID 30018735, 2018). "Macrophages are the most dominant innate immune cell type in tumor control, and they are the main sources of TNF." (PMID 29892300, 2018). "In a mouse model of melanoma, TNF injection favored tumor metastasis by acting on TNFR2-expressing hematopoietic cells, which was associated with an increase of Tregs." (PMID 29593717, 2018). "TNFα derived from cells in the tumor microenvironment can activate proinflammatory and pro-survival pathways in tumor cells, such as those mediated by the NFκB transcription factor family." (PMID 30349042, 2018). "RDW elevation is strongly associated with the increase of other inflammation markers, such as interleukin-6 and tumor necrosis factor-α that can affect the tumor cell biological behaviors." (PMID 29643918, 2018). "On the other hand, TNF-α also has inherent anti-tumor effects: the cytokine activates tumor-infiltrating dendritic cells and promotes tumor stroma destruction." (PMID 29996539, 2018). "Since STAT3 is a well known downstream effector of IL-6 and TNF-alpha, these data further support the ability of trabectedin to inhibit proinflammatory cytokines secretion from senescent tumor cells." (PMID 29731994, 2018). "Tumor necrosis factor develops tumor invasion in CRC through c-Src oncogene activation, as it promotes angiogenesis, proliferation, and metastasis." (PMID 29930913, 2018). "As a tumor-necrotizing agent, TNF’s toxicity in animal models was apparently acceptable, thus TNF was quickly launched into clinical trials." (PMID 29751683, 2018). "CD4+ Th1 cells produce high levels of IFN-γ and TNF-α upon antigen stimulation and take charge of cell-mediated immunity to intracellular pathogens and tumor cells, while CD4+CD25+ Tregs mediate immune suppression." (PMID 30309387, 2018). "Our previous studies indicated that the MK2 pathway regulates IL-1β, IL-6, and TNF-α in CRC tumor models." (PMID 30298062, 2018). "In this model, production of IFN-γ, IL-2, and TNF-α showed a sharp threshold dependence on tumor antigen density and there was a significantly higher threshold for IL-2 production compared to IFN-γ production." (PMID 30416506, 2018). "Expression of the adenovirus E1A oncogene sensitizes tumor cells to innate immune rejection by apoptosis induced by macrophage-produced tumor necrosis factor (TNF)-α and nitric oxide (NO)." (PMID 30245858, 2018). "The expression of serum IL-2 and IFN-γ in model group was notably reduced while TNF-α was notably increased on account of the transplanted tumor (p < 0.05)." (PMID 30966454, 2018). "It is assumed the stimulation of the TNF-α/TNFR1 signaling in the tumor microenvironment enhances GC progression by inducing Noxo1 and GNA14." (PMID 29867530, 2018). "It has also been demonstrated that probiotic L.rhamnosus GG induced the macrophage activation, nitric oxide production by macrophages and significantly increased the production of TNF-α which can be cytotoxic or cytostatic to tumor cells." (PMID 30424722, 2018).
tumor (continued). "The controversial role of TNF, reported to both inhibit and promote cancer growth, has been explained by the ability of tumor cells to attract TNF-secreting cells through MHC class II molecules expression." (PMID 30591049, 2018). "In a tumor context endothelium is affected by the microenvironment, thus a pro-inflammatory cytokine known to activate endothelial cells (TNF-α) was added in the receptor chamber to simulate such altered environment." (PMID 30311803, 2018). "The pro-inflammatory cytokines, i.e. tumor necrosis factor-α (TNF-α), interleukin-1β (IL-1β), and IL-6, activate inflammation, as proposed for the deterioration of angiogenesis in tumor cells." (PMID 30479366, 2018). "These facts indicated that the TNF‐α‐enhanced expression of miR‐130b protected the tumour cell from the apoptosis induced by TNF‐α." (PMID 29632814, 2018). "The role of TNF is, however, controversial, where some studies have shown high concentrations of TNF- α to act as a tumour suppressor in animal models whereas low levels in contrast can induce cancer." (PMID 29924765, 2018). "TNFα is a pleiotropic cytokine, which plays a dual role in the tumor microenvironment by controlling various functions such as apoptosis, invasion and proliferation." (PMID 30647851, 2018). "TNF-α is an important inflammatory factor, and multiple lines of evidence point to the critical role of TNF-α in tumor proliferation, migration, invasion, and angiogenesis." (PMID 29531823, 2018). "Significantly enhanced TNF-α serum cytokine level (316 ± 53 ng/ml) was noted for HIFU plus TB mice tumor groups compared to untreated control (58.3 ± 1.15 ng/ml), HIFU (84.7 ± 3.93 ng/ml) and Salmonella (110.48 ± 7.82 ng/ml) treated mice." (PMID 30166607, 2018). "TNF-α gene was first cloned in 1985 and it is expressed in diverse cells including macrophages and tumour cells." (PMID 30300401, 2018). "Inflammatory macrophages contribute to cancer immunotherapy by killing tumor targets via the secretion of various mediators including TNFα." (PMID 29632539, 2018). "TNF-α can facilitate the generation and maintenance of anti-tumor immune responses through the activation of NK cells and CD8+ T cells." (PMID 29361917, 2018). "Increased production of IFN-γ, GM-CSF, and TNF-α was observed in the supernatants of PNK-007 co-cultured with GBM cell lines compared with those of PNK-007 alone or tumor cells alone." (PMID 30400835, 2018). "Inflammatory cells such as TAMs are recruited to the tumour stromal interface and along with CAFs secrete cytokines including TNF-α and TGF-β to control the inflammatory response and to activate wound healing programmes." (PMID 29416729, 2018). "Src can increase pro-inflammatory cytokines production for tumor development and activate survival effectors for chemoresistance, including TNF-α, IL-1β, IL6, phosphoinositide 3-kinases (PI3Ks), AKT and STAT3." (PMID 30473665, 2018). "Regarding dietary fiber, a polysaccharide from Lentinus edodes mushroom suppressed tumor growth in nude mice, upregulated caspase-3, -9 activity, increased Bax/Bcl2 ratio, increased the generation of free radicals in tumor tissues and TNF-α production." (PMID 30487390, 2018). "IL-18 induced the secretion of IFN-γ, IL-2, GM-CSF, TNF-α by the NK cells, and these secreted cytokines exert antitumor effects by directly killing tumor cells or regulating the immune function." (PMID 30002398, 2018). "TNF-α as a pro-inflammatory cytokine is mainly produced by monocytes, macrophages, initial hemorrhages, and necrosed tumor tissues." (PMID 29357879, 2018).
tumor (continued). "The results strongly indicated that induction of TNF-α gene expression by a tumor promoter in vitro is similar to tumor-promoting activity in vivo." (PMID 30341686, 2018). "Some of these compounds significantly inhibited mitogen-induced proliferation of human peripheral blood mononuclear cells, tumor necrosis factor alpha (TNFα) production in human whole blood cultures and the growth of tumor cell lines." (PMID 30250011, 2018). "These ADAMs regulate the activation of growth factors (e.g., EGF, TGF-a), cytokines (TNF-a), and integrins, which in turn promote tumor growth and metastasis." (PMID 29776401, 2018). "To demonstrate this assumption, we transfected miR‐130b inhibitors or their scrambled controls into TNF‐α‐ or vehicle‐treated tumour cells." (PMID 29632814, 2018). "To evaluate the role of TNFα-mediated Ca2+ influx in tumor growth in vivo, we established the subcutaneous nude mice model." (PMID 29506556, 2018). "NK-cell derived IFN-γ, in concert with TNF-α produced by the injected DCs and also by activated NK cells, will enhance cross-presentation of captured tumor antigens by recruited, endogenous, DCs." (PMID 29904904, 2018). "Several pro-inflammatory mediators that have been shown to alter the tumor microenvironment, including members of the Tumor Necrosis Factor (TNF)-superfamily, are regulated by the transcription factor NF-κB." (PMID 30002278, 2018). "Connecting a wide variety of cell types, TNF constitutes itself a central player in the multi-faceted tumor microenvironment." (PMID 29892300, 2018). "Second, the anti-tumorigenic effects of the TNF-α/IFN-γ-induced-ASCs on TNBC in vivo are dependent on tumor size, suggesting the importance of crosstalk between induced-ASCs and tumor cells." (PMID 29330447, 2018). "Induction of S100A8 and S100A9 expression in response to primary lung tumor cell-derived soluble factors VEGF-A, TGF-β and TNF-α in myeloid cells prior to tumor metastasis has been reported." (PMID 30558665, 2018). "Among tumor-secreted pro-osteolytic molecules, there are PTHrP, Interleukin-6 (IL-6), IL-1, Tumor Necrosis Factor α (TNFα), IL-8, IL-11, M-CSF, TGF-β, Vascular Endothelial Growth Factor (VEGF), Matrix metalloproteinases (MMPs), and prostaglandins." (PMID 29890702, 2018). "In attempt to control the potential pro-tumor effects of TNF-alpha, human clinical trials were conducted using anti-TNF antibodies or receptors and these have met with limited disease stabilization in approximately 20% of the patients." (PMID 30170620, 2018). "Consistent with earlier findings, R848-treated mMDSCs lysed tumor targets as did cells cultured with IFNγ or the combination of IL-6 plus TNFα." (PMID 29632539, 2018). "Tumour necrosis factor alpha (TNF‐α) is a multifunctional cytokine and has the capacity both to promote cell growth and to kill tumour cells by inducing cell apoptosis." (PMID 29632814, 2018). "It has been reported that one pathway for DC‐CIK cells to kill tumour cells is to secrete some tumour‐killing factors such as TNF‐α and IFN‐γ." (PMID 29566310, 2018). "To provide evidence that the TNF/death receptor pathways are activated in the regressing tumor, we conducted IHC analysis for cleaved caspase 8 in regressing and non-regressing tumors." (PMID 30323292, 2018). "NF-κB activation is essential in protecting transformed cells from macrophage-induced apoptosis during tumor initiation through the upregulation of TNF and nitric oxide." (PMID 30060453, 2018). "The classical activation of M1 macrophages can induce the release of pro-inflammatory cytokines such as IL-12 and tumor necrosis factor (TNF) and play a role in killing tumor cells." (PMID 30115069, 2018). "H. pylori, through NF-κB induction on tumor cells, reduces the expression of FAF1, promoting cell survival, and induces the inflammatory cytokines TNF-α and IL-8, which is associated to tumor growth." (PMID 29315242, 2018).
tumor (continued). "Mechanistic studies indicated that the compound 12 can inhibit TNF-α induced NF-κB activation, thereby inducing tumor cell apoptosis." (PMID 29557523, 2018). "Six patients with one or more neoplasms during or after anti-TNF exposure were identified resulting in a malignancy rate of 1.68%." (PMID 29540190, 2018). "Numerous mouse studies have shown that anti-TNF drugs reduced tumor growth in different types of cancers." (PMID 29593717, 2018). "In the same way, different proinflammatory cytokines, like IL-6 and TNF-α, are described as tumor promoters and are related to poor prognosis." (PMID 29315242, 2018). "Neutrophilia can occur in cancer patients at a peripheral level, but neutrophils can also localize to the tumor due to multiple factors, including general inflammatory signals such as IL-1 and TNF-α." (PMID 30012216, 2018). "SLP vaccination has recently been shown to synergize with a suboptimal dose of cisplatin in the eradication of TC-1 tumors in mice, partially explained by the enhanced apoptosis of tumor cells by TNFα from SLP-induced T cells in the presence of cisplatin." (PMID 30541631, 2018). "Briefly, dCAR-T cells in mice bearing the cognate tumor cells (AsPC-1) released high levels of cytokines, including 2320 pg/mL IL-2, 609 pg/mL TNFα, 2486 ng/mL IL-6, and 67 ng/mL IFNγ, which was similar to that observed for cytotoxicity." (PMID 30103775, 2018). "The effective abscopal antitumor activity by E7766 was mediated by type I IFN signaling, CD8 T cells, and TNFα, and the tumor free mice completely rejected rechallenges of the same tumor in the absence of CD8 T cells or NK cells." (PMID 30400822, 2018). "It has been proposed that IL-1 mediates cytotoxicity and suppression of tumor growth and TNF-α inhibits angiogenesis to prevent tumor growth." (PMID 30365491, 2018). "TNF promotes tumor angiogenesis by up-regulating the expression of several members of the vascular endothelial growth factor family." (PMID 29765518, 2018). "Antibiotic-induced dysbiosis in mice model promotes intestinal inflammation and thus produce higher levels of pro-inflammatory cytokines including tumor TNF-α, IL-1β, MCP-1, and IFN-γ." (PMID 30065236, 2018). "The anti-tumor effects of TNF-alpha have been demonstrated on primary tumors with significant pancancer effects through vascular destruction and tumor necrosis." (PMID 30170620, 2018). "For example, in the Lewis Lung Model, knock down of TNF-R2 in the cancer cells promotes robust anti-tumor effects upon administration of low dose murine TNF-alpha whereas in wild type mice it enhanced tumor growth while the TNF-R1 knockdown was not affected." (PMID 30170620, 2018). "Animal models have shown a positive relationship between TNF-α and tumor development and progression in CRC." (PMID 30581847, 2018). "This phenomenon significantly increases the amount of inflammatory cytokine IL-1β, TNF-α and Il-18 in tumors, which results in drastic tumor growth suppression." (PMID 29568324, 2018). "Our findings demonstrate that the addition of TNFα dramatically increased tumor invasion and growth." (PMID 30018735, 2018). "Beside the generally accepted apoptosis-inducing and anti-tumor activity of TNF-α, it can also promote metastasis of tumor cells by inducing the chemokine receptors on the tumor cells particularly in late stage cancers." (PMID 29588627, 2018).
tumor (continued). "Although TNF-α and II-17A expression was significantly upregulated in untreated tumor-bearing mice compared to naïve mice, their expression in the sera of the induced-ASC treated group was reduced relative to the vehicle group but not back to naïve levels." (PMID 29330447, 2018). "The augmented CD200 expression not only attenuates antigen-specific Th1 cytokines such as IFNγ and TNFα production but also direct them to acquire Th2 phenotype (expression of IL-4/IL-10 cytokines in viral and tumor pathogenesis)." (PMID 29915577, 2018). "A lack of TNF-α has been correlated with resistance to skin carcinogenesis, which corroborates our findings indicating the presence of a direct relationship between high TNF-α levels and tumor development." (PMID 30112116, 2018). "6/357 (1.68%) rheumatology patients treated with anti-TNF therapy between 1997 and 2013 developed neoplasms." (PMID 29540190, 2018). "Although TNF-α has been shown to both inhibit and promote tumor growth, chronically produced TNF-α enhances tumor development in several cancer types." (PMID 29784005, 2018). "TNF-α and chemokines increase vascular permeability and promote the extravasation and migration of tumor cells." (PMID 29662489, 2018). "TNF-α is a major cytokine in the tumor microenvironment and its expression correlates with the GBM tumor grades." (PMID 29301329, 2018). "Previous studies support our result that TNFα is mainly expressed by activated immune cells especially macrophages and T cells, but can also be produced by tumor cells and capable of exhibiting anticarcinogenic effect in various subtypes of cancer." (PMID 30701020, 2018). "Pro-inflammatory (such as IL-6 and TNF-α) and proliferative (like leptin and insulin) factors are considered as tumor growth favoring molecules." (PMID 29568521, 2018). "In contrast, M1 macrophages, also known as classically activated or killer macrophages, express nitric oxide synthase (NOS2) and TNF-α and orchestrate protective anti-tumor immune responses." (PMID 29765907, 2018). "The secretion of pro-inflammatory cytokines, including TNF, IL-1, and IL-8, is believed to build an inflammatory environment allowing tumor growth and metastasis." (PMID 30149677, 2018). "Unfortunately, the cytotoxic effect of TNF‐α is cell line specific and only a proportion of tumour cell lines are sensitive to TNF‐α cytotoxicity." (PMID 29632814, 2018). "We observed up-regulation (more than 2 standard deviations) of number of pro-inflammatory cytokines (G-CSF, GM-CSF, IFN-γ, IL-1β, IL-17, TREM-1, TNF) in mice with three-week tumors as compared to one-week tumor." (PMID 30323345, 2018). "Activated Vδ2 T cells shortly produce huge amount of IFN-γ, TNF-α that play a central role in controlling tumor and infections." (PMID 29928279, 2018). "Treatment with DMBA plus TPA delayed tumor onset in TNF−/− mice 4 weeks, and the time to develop to 100% was 9 weeks later than that in TNF+/+ mice." (PMID 30341686, 2018). "OK-432 has been reported to activate immunocompetent cells such as macrophages, T cells, and natural killer (NK) cells, and exerts an anti-tumor effect by these cells producing IL-1, IL-2, IL-6, tumor necrosis factor (TNF)-α and IFN-γ." (PMID 30486312, 2018). "The pro-tumor actions of inflammatory cells include: the presence of leukocyte infiltration; the expression of cytokines such as tumor necrosis factor (TNF) or IL-1; chemokines such as CCL2 and CXCL8; active tissue remodeling and neo-angiogenesis." (PMID 29751789, 2018). "Further analysis revealed that the increased CD8 TILs in CP1-administered tumors expressed increased TNFα and the activation marker PD-1, and a higher percentage expressed IFNγ within the tumor draining lymph nodes (dLNs)." (PMID 29686284, 2018). "We have shown that an oncolytic adenovirus expressing IL-2 and TNF-α enhanced the efficacy of mesothelin-redirected CAR T cells, which was associated with enhanced T cell infiltration to the tumor bed and reduced metastases." (PMID 30416506, 2018).